ARMCX1 (armadillo repeat containing X-linked 1)
Description:
Regulates mitochondrial transport during axon regeneration. Increases the proportion of motile mitochondria by recruiting stationary mitochondria into the motile pool. Enhances mitochondria movement and neurite growth in both adult axons and embryonic neurons. Promotes neuronal survival and axon regeneration after nerve injury. May link mitochondria to the Trak1-kinesin motor complex via its interaction with MIRO1.
Synonyms: ALEX1; GASP7
Tractability: Antibody: UniProt predicts a signal peptide or a membrane-spanning region. PROTAC: ubiquitination databases record sites on it; its protein half-life has been measured.
Gene: Protein-coding gene on chromosome X (101,550,411 to 101,554,704, forward strand). Ensembl gene ENSG00000126947.
Subcellular location: Mitochondrion; Mitochondrion outer membrane
Subcellular location (Human Protein Atlas): Mitochondria; Cytosol; Nucleoplasm
Gene Ontology:
Molecular function: protein binding
Biological process: axonal transport of mitochondrion
Cellular component: mitochondrion; mitochondrial outer membrane; axon cytoplasm
Homologues: Orthologues: chimpanzee ARMCX1 (99% identical), macaque ARMCX1 (99% identical), rabbit ARMCX1 (89% identical), dog ARMCX1 (89% identical), pig ARMCX1 (87% identical), guinea pig ARMCX1 (85% identical), rat Armcx1 (85% identical), mouse Armcx1 (85% identical), tropical clawed frog armc10 (24% identical), zebrafish armc10 (23% identical), Caenorhabditis elegans Y67A10A.7 (13% identical). Paralogues in human: ARMCX2 (42% identical), ARMCX3 (41% identical), ARMC10 (36% identical), ARMCX4 (35% identical), ARMCX6 (22% identical), GPRASP1 (22% identical), GPRASP2 (21% identical), ARMCX5 (20% identical), GPRASP3 (15% identical), ARMC12 (13% identical).
Diseases named in the same sentence as ARMCX1 in open-access papers:
ARMCX1 is named in the same sentence as 26 diseases in open-access papers, as found by Europe PMC text mining. Sharing a sentence is not in itself a finding about the gene and the disease. The quoted sentences say what the papers report.
gastric cancer (6 papers, 2020 to 2024). A primary or metastatic malignant neoplasm involving the stomach. "The function of ARMCX1 is relatively unknown, but a recent study reported that ARMCX1 is associated with RNA modification and damage response and could be a potential prognostic marker of gastric cancer." (PMID 34065963, 2021). "This study helps the improvement of evaluating the prognosis of gastric cancer patients, and would help optimize chemotherapeutic strategies in consideration of the expression of ARMCX1." (PMID 36726491, 2023). "The altered expression of ARMCX1 in patients with gastric cancer has been reported frequently, yet its correlation to prognosis and chemotherapy needs to be unveiled." (PMID 36726491, 2023). "For better validating ARMCX1 protein level, this work visualized IHC staining data in HPA and showed markedly enhanced ARMCX1 staining within glandular cells in healthy stomach samples, whereas gastric cancer tissues had low ARMCX1 staining." (PMID 35571487, 2022). "The IMAGiC model predicts response to ICI in patients with advanced gastric cancer based on the expression signature of four genes (ubiquitin C-terminal hydrolase L1 [UCHL1], tyrosine kinase 2 [TYK2], protein kinase D1 [PRKD1], and armadillo repeat-containing X-Linked 1 [ARMCX1])." (PMID 37877810, 2024). "Nonetheless, ARMCX1's clinicopathological and prognosis significance within gastric cancer (GC) is still unknown." (PMID 35571487, 2022). "More importantly, ARMCX1 and ARMCX2 are more highly expressed in adjacent normal tissues than in tumor tissues, leading to better OS in patients with gastric cancer, although the mechanism of action needs further clarification." (PMID 32685472, 2020). "On the basis of GSEA results, we deduced that both ARMCX1 and ARMCX2 were involved in the pathway and biological processes that are associated with the progress and treatment of gastric cancer and may serve as a GC prognostic marker." (PMID 32685472, 2020).
prostate carcinoma (4 papers, 2017 to 2025). A carcinoma that arises from epithelial cells of the prostate gland. "The possible prostate cancer (PCa) diagnostic biomarkers AOX1, APOC1, ARMCX1, FLRT3, GSTM2, and HPN were identified and validated using the GSE69223 and GSE71016 datasets." (PMID 37583929, 2023). "In our study, we identified AOX1, APOC1, ARMCX1, FLRT3, GSTM2, and HPN as biomarkers associated with prostate cancer (PCa)." (PMID 37583929, 2023). "ARMCX1 has been reported in various human tissues, including lung cancer, prostate cancer, colon cancer, pancreatic cancer, and ovarian cancer." (PMID 36726491, 2023). "It was reported that downregulated ARMCX1 transcripts have been found to be significantly reduced prostate cancer and may play a role of tumor suppressor gene." (PMID 29110633, 2017). "The genes ITGBL1, DSC3, COL4A6, ANGPT1, ARMCX1, MICAL2, and EPHA5 have been recognized as pivotal genes that substantially affect the microenvironment of prostate cancer." (PMID 40943497, 2025). "Very little is known about the functional properties of these two genes, this could make ARMCX1 and CLIC2 the possible candidates of medical relevance, such as prostate cancer in male and oxidative stress-related diseases for female." (PMID 29110633, 2017).
breast carcinoma (2 papers, 2017 to 2018). "For females the top hit was ARMCX1 (p-value = 6.07e-4), a tumor suppressor gene involved in cell proliferation and apoptosis of breast cancer cells." (PMID 30713548, 2018). "To exclude the possibility that ARMCX1, ENPP1 and MCT2 are essential for breast cancer growth regardless of the MGDAs, we tested whether colony formation was enhanced by MGDAs in MDA-MB-468 and SK-BR3 cells ectopically expressing these genes." (PMID 28281525, 2017).
colorectal cancer (2 papers, 2009 to 2022). A primary or metastatic malignant neoplasm that affects the colon or rectum. "ARMCX1 is identified as a prognostic biomarker in ovarian cancer, colorectal cancer and also in cervical cancer." (PMID 35184747, 2022).
brain tumour (1 paper, 2023). "Several negatively correlated genes, including FGF9, ARMCX1, PMP22, and ZBTB18 are involved in nervous system functions, such as glial cell growth, axon regeneration, myelin development and brain tumour suppression." (PMID 37077524, 2023).
cholangiocarcinoma (1 paper, 2023). A carcinoma that arises from the intrahepatic biliary tree (intrahepatic cholangiocarcinoma) or from the junction, or adjacent to the junction, of the right and left hepatic ducts (hilar cholangiocarcinoma). "The analysis with TIMER showed that ARMCX1 was drastically lower in various cancerous tissues, such as malignant bladder, breast, uterine neck, colon, kidney, lung, prostates, stomach, and thyroid; while ARMCX1 expression was higher in cholangiocarcinoma." (PMID 36726491, 2023).
gastric tumors (1 paper, 2020). "ARMCX1, ARMCX2, and ARMCX4 were lowly expressed in primary gastric tumors and has a high expression in normal gastric tissues." (PMID 32685472, 2020).
ischemic heart disease (1 paper, 2023). "Prex1 and Irx3 are suggested as potential modifier genes of cardiac Cu content, while Ctsa, Mmp2, and Armcx1 may closely be related to ischemic heart disease." (PMID 36818345, 2023).
leukemia (1 paper, 2021). A malignant (clonal) hematologic disorder, involving hematopoietic stem cells and characterized by the presence of primitive or atypical myeloid or lymphoid cells in the bone marrow and the blood. "It has been reported that the absence of ARMCX1 enhances the regeneration of hematopoietic stem cells and may thus regulate leukemia, myelodysplastic syndrome (MDS), metastatic cancer, and autoimmune diseases (AIDs)." (PMID 34912852, 2021). "Regarding tissue development and differentiation, it has been reported that the absence of ARMCX1 enhances the regeneration of hematopoietic stem cells and may thus regulate leukemia and MDS." (PMID 34912852, 2021).
metastatic cancer (1 paper, 2021). A carcinoma which has spread from the original site of growth to another anatomic site. "Regarding tissue development and differentiation, it has been reported that the absence of ARMCX1 enhances the regeneration of stem cells and may thus regulate metastatic cancer." (PMID 34912852, 2021).
soft tissue sarcoma (1 paper, 2020). A malignant neoplasm arising from muscle tissue, adipose tissue, blood vessels, fibrous tissue, or other supportive tissues excluding the bones. "Among the identified genes linked with mesenchymal traits, expression of the ARMCX1 gene, which encodes mitochondria-localized armadillo repeat-containing X-linked protein 1, was revealed as a very strong predictor of poor outcome in soft-tissue sarcomas." (PMID 31941033, 2020). "This is in agreement with our survival analysis on soft-tissue sarcomas demonstrating that upregulated expression of ALDH6A1 but not ALDH1A1 or ALDH3A1 significantly correlates with poor survival when combined with other genes identified in our model, i.e., CDH15, MYOD1, SOX4, ARMCX1, and RYK." (PMID 31941033, 2020).
tuberculosis (1 paper, 2018). A chronic, recurrent infection caused by the bacterium Mycobacterium tuberculosis. "While this gene has not been previously implicated in TB susceptibility, M. tuberculosis has been shown to affect apoptosis pathways in order to evade the host immune response, suggesting that ARMCX1 could affect TB susceptibility." (PMID 30713548, 2018).
tumor (10 papers, 2009 to 2025). "ARMCX1 (Armadillo repeat containing X-linked 1) is identified to be the novel tumor suppressor gene related to multiple tumor types." (PMID 35571487, 2022). "As a result, certain tumor-associated pathways were markedly associated with ARMCX1 upregulation within GC, which included focal adhesion, extracellular matrix receptor interaction, chemokine signaling, cancer, Wnt pathway, and Toll-like receptor pathway." (PMID 35571487, 2022). "Nomogram risk scoring includes age, tumor stage, and the expression level of ARMCX1 and ARMCX2 to calculate 1-year, 5-year, and 10-year related survival rates." (PMID 32685472, 2020). "Correlation analysis revealed that ARMCX1 expression was significantly positively associated with eight tumor-infiltrating immune cell types, while six other tumor-infiltrating immune cells were negatively correlated with ARMCX1 expression." (PMID 36726491, 2023). "A significant reduction in ARMCX1 expression level was observed in tumor tissues compared to healthy samples from TCGA and GEO." (PMID 37397364, 2023). "Based on these findings, ARMCX1 is the potential tumor suppressor during cancer occurrence and development." (PMID 35571487, 2022). "Relations of ARMCX1 with clinicopathological variables, such as age, sex, tumor stage, tumor grade, invasion depth, DM, and LNM, were analyzed." (PMID 35571487, 2022). "According to subsequent analyses, ARMCX1 overexpression was related to age, local invasion depth, clinical stage, and tumor grade." (PMID 35571487, 2022). "Other regulated signalling molecules included guanine exchange factors that play a role in an activation of the MAP kinases while several tumor suppressors i.e. Mcc, Hey1, Fat3, Armcx1 and Reck were significantly repressed." (PMID 19812696, 2009). "Therefore, the present study provides insights into the protective role of ARMCX1 in tumor immunology and its potential as a prognostic biomarker for GC." (PMID 36726491, 2023). "Interestingly, ARMCX1 upregulation predicted low differentiation, poor OS, increased invasion, and late tumor stage." (PMID 35571487, 2022). "Based on the results of this study, the correlations between ARMCX1 expression and TME score, tumor infiltrating immune cells, immune checkpoints, and TMB may be useful to the development of novel cancer therapies." (PMID 36726491, 2023). "According to one latest work, ARMCX1 level decreased within human GC samples compared to nontumor samples and is correlated with tumor stage and TNM (tumor-node-metastasis) staging." (PMID 35571487, 2022). "The higher total points, the lower survival rate, and the results substantiated that high expression levels of ARMCX1 and ARMCX2, age of the patient (>60 years old), and advanced tumor stage established a prognostic feature that conduced to the highest risk for poor OS." (PMID 32685472, 2020).
cancer (3 papers, 2020 to 2023). A tumor composed of atypical neoplastic, often pleomorphic cells that invade other tissues. "Using a pancancer analysis of TIMER databases, we examined the relationship between ARMCX1 and multiple cancer tumorigenesis models." (PMID 36726491, 2023). "This work conducted bioinformatics analyses on ARMCX1 expression profiles in GEO and TCGA databases, and ARMCX1 was significantly reduced within cancer tissues in comparison with healthy samples, consistent with a previously published studies." (PMID 35571487, 2022). "Reduced or even undetectable ARMCX1 level is reported within several cancers, like lung cancer (LC), liver cancer, pancreatic cancer, colorectal cancer (CRC), prostate cancer (PCa), and ovarian cancer (OC), and is associated with adverse outcomes." (PMID 35571487, 2022). "ARMCX1 level was significantly lower within the cancer samples in comparison with healthy samples (P = 0.002)." (PMID 35571487, 2022). "Scholars have found that some members of the ARMCX protein family (Armcx1-3) were underexpressed in several cancers of epithelial origin, including the lung, prostate, colon, and pancreatic." (PMID 32685472, 2020). "Importantly, ARMCX1 mRNA is critical downregulated or even undetectable in several carcinomas." (PMID 35571487, 2022).
ARMCX1 also shares sentences with these, for which no sentence is quoted: colon cancer (2 papers); lung carcinoma (2); ovarian carcinoma (2); adenocarcinoma (1); cervical cancer (1); cervical squamous cell carcinoma (1); infection (1); Mcc (1); melanoma (1); myelodysplastic syndrome (1); osteoporosis (1); pancreatic cancer (1).